CD8A (CD8 subunit alpha)
Diseases named in the same sentence as CD8A in open-access papers (continued):
Sharing a sentence is not in itself a finding about the gene and the disease.
infection (continued). "The most important parameters include accumulation and activation of CD8α+ DCs at site of infection which is crucial for long-lasting immune responses against LS Plasmodia infection." (PMID 29472929, 2018). "ADRV specifically down-regulated the expression of some host genes, such as MHC I-1 and CD8 (A and B) at the early stage of infection, as well as perforin, a key executor of cytotoxic lymphocytes." (PMID 29558886, 2018). "In BATF3−/− mice lacking CD8α+ DCs, ISG15 fails to induce an IL-1β increase during Toxoplasma infection, as seen in B6 mice, demonstrating that ISG15 induces IL-1β–producing CD8α+ DCs at the site of infection." (PMID 29891555, 2018). "Increased ISG15 is concurrent with an influx of IL-1β–producing CD8α+ dendritic cells to the site of infection." (PMID 29891555, 2018). "Spz inoculation promotes the greater accumulation of CD8α+ DCs to the site of infection probably by modulating the liver microenvironment." (PMID 29472929, 2018). "We found that ISG15 levels correlate with an increase of IL-1β levels in the serum and with increased number and frequency of CD8α+ conventional DCs at the site of infection." (PMID 29891555, 2018). "In the context of Toxoplasma infection, different studies have shown that CD8α+ DCs are a critical source of IL-12 during the acute phase of infection and relocate to the T cell area of the spleen to promote IFN-γ production by T cells." (PMID 29891555, 2018). "The presence of free ISG15 enhances the production of IL-1β by CD8α+ DCs present at the site of infection." (PMID 29891555, 2018). "suggestive of the fact that greater accumulation of CD8α+ DCs at the site of infection is because of the infectious status of the sporozoite." (PMID 29472929, 2018). "Mice treated with ISG15-C76S/C144S resembled untreated wild-type mice, confirming that cysteine residues of ISG15 are critical to facilitate CD8α+ DC recruitment to the site of infection." (PMID 29891555, 2018). "Utilizing mice that express the diphtheria toxin receptor under control of the langerin promoter, we investigated the impact of depleting langerin+ CD8α+ DCs in a murine model of intravenous infection with Mycobacterium bovis bacille Calmette–Guerin (BCG)." (PMID 29867941, 2018). "Quantification of splenic CD11b+ and CD8α+ cDCs from control or LDV‐infected mice showed that both were severely diminished after infection (CD11b+: 4.3 ± 0.3 vs. 0.53 ± 0.03 × 105 and CD8α+: 5.3 ± 0.7 vs. 0.58 ± 0.09 × 104)." (PMID 28474504, 2017). "Infection with P.y-WT or P.y-GPC3 led to a decrease in percentage of splenic CD8α- CD11C+ DCs compared with uninfected mice (0.486% or 0.578%, vs 2.23%)." (PMID 28445973, 2017). "In a previous report, CD103+CD62LlowCD69+ CD8α+ T cells were shown to be generated at the site of viral or bacterial infection and retained until secondary infection." (PMID 28296922, 2017). "We established mouse model of schistosomiasis infection in B6 mice and detected the number of CD8α+DCs in the spleen at 0, 3, 6 and 9 weeks post-infection." (PMID 28646891, 2017). "The other splenic DC subset is CD8α+ conventional DCs (cDCs), and it is responsible for the final resolution of infection against Listeria through the antigen presentation of bacterial-derived antigens to specific CD8+T cells to induce cytotoxicity." (PMID 29281743, 2017). "These CD103+CD62LlowCD69+CD8α+ T cells are referred to as resident memory T cells (Trm cells), and are able to intercept and eradicate pathogens immediately at sites of infections (skin or intestinal mucosa)." (PMID 28296922, 2017). "The expression of T cell specific transcripts including Cd8a and Ifng, was strongly up-regulated in the brain 7 days post-PbA-infection in WT mice, as compared to naïve control mice." (PMID 28448579, 2017). "Surprisingly, there was still a small amount of CD8α+ DCs in the spleen of Batf3−/− mice at 9 weeks post-infection." (PMID 28646891, 2017).
infection (continued). "Both TCR (CD3ε gMFI) and co-receptor (CD8α gMFI) levels were unchanged in either the spleen or the brain over the course of infection with MuPyV.TagV or the analogue viruses." (PMID 28410427, 2017). "Surprisingly, the majority (> 65%) of IL-10gfp+ skin cells on day 6 post-recombinant vaccinia virus (rVV)-infection of TIGER mice were CD8+ T cells, as defined by the cell-surface markers CD45, CD8α, and CD8β." (PMID 26991092, 2016). "A significant induction of IL-12p40 mRNA synthesis was observed in neonatal and adult CD8α- DCs and in adult CD8α + DCs upon Lm actA-/- infection." (PMID 27074026, 2016). "Overall, the CD8α protein distribution preference and viral antigen location showed similar distributions, which suggested an immunoregulatory function in infection defence." (PMID 27150912, 2016). "Specific NK-mediated control of MCMV has been shown to protect CD8α DC, which reciprocally affect the expansion of NK cells after infection, and the balance of NK-DC crosstalk has considerable potential to affect T cell immunity." (PMID 26845690, 2016). "The accumulation of CD3+CD4+and CD3+CD8α+ lymphocytes in the magnum was greater in the experimental than in the control group throughout the course of infection." (PMID 27846843, 2016). "In contrast, WASp KO mice showed no increased numbers of MHC class IIhigh DCs or CD103+, CD8α+ and CD8α− DCs in the dLNs upon infection." (PMID 27425374, 2016). "The absolute numbers of both CD11b+ and CD8α+ DCs increased at the site of infection (peritoneal cavity) until reaching a peak by day 5 after infection." (PMID 27057101, 2016). "CD8α+ DCs were only required to cross present YopE peptide if infection was carried out with strain ΔBmE, since the levels of ET cells in the Batf3-/- mice infected with ΔBmE decreased to the levels seen in mice left uninfected." (PMID 26468944, 2015). "Another interesting finding here is the requirement of CD8α+ DCs, in eliciting the ET cells by a “translocation-independent” pathway during infection with a Y. pseudotuberculosis yopB mutant." (PMID 26468944, 2015). "Recipients of CD4+ and CD8α+ cells showed significant resistance to infection with E. tarda eight days after sensitization, indicating that helper T cells and cytotoxic T lymphocytes play crucial roles in protection against E. tarda." (PMID 26426066, 2015). "By respective gates, Ki-67+CD4+ T cells were separated into naïve CD8α− cells and antigen-experienced CD8α+ cells and, again, absolute numbers were calculated in the time course following infection." (PMID 25971313, 2015). "Our results here indicated that during infection with the yopB mutant, secreted YopE is taken up and cross-presented by the CD8α+ DCs in vivo." (PMID 26468944, 2015). "In animals #6, #7 and #8, we observed a slight increase of Ki-67+CD4+ T cells, one or two weeks after primary infection, with the majority of proliferating cells expressing the activation marker CD8α." (PMID 25971313, 2015). "The lower parasitic burden detected in thebrain of CD8a−/− mice 40 dayspost-infection as compared to that detected in 7-day infected animals also indicatesthat other cell populations than CD8+ T cells mediate immuneprotection in the brain." (PMID 26449650, 2015). "While both the groups of mice receiving CD8α+ and CD8α− DCs from WT mice showed significant resistance to infection compared to those from Jα18-KO mice, the WT CD8α+ DC recipients had superior protection." (PMID 26029217, 2015). "We have based our analysis on the immunodominant CS protein; however, it is possible that CD8α+ DCs present additional liver stage antigens in the liver draining lymph nodes or the liver site of infection." (PMID 25658939, 2015). "Mice that are missing CD8α+DC succumbed to infection in the aftermath of exposure to infectious sporozoites." (PMID 26074888, 2015).
infection (continued). "Three weeks after infection, many unigenes were involved in adaptive immunity, including immunoglobulin IgG heavy chain, Fc receptor of IgE and CD8A antigen protein complex, CD74." (PMID 24886088, 2014). "The proportion of the CD2+CD8α— γδ T cell subset was comparable to GF animals in all three infections." (PMID 25186625, 2014). "Similar to CD21− B cells, total numbers of CD4+CD8α+ T helper cells dropped less severely than CD4+CD8α− T helper cells in INOC gilts on 2 dpi after PRRSv infection." (PMID 25497114, 2014). "Accordingly, one day after infection, CD8α+ DCs were purified from the spleen of WT and HVEM−/− mice and examined for their ability to induce proliferation of naive CFSE-labeled WT OT-I cells directly ex vivo." (PMID 24205056, 2013). "During infection, the percentage CD8α+ NK cells varied, and only at 5 dpi the percentage of CD8α+ NK cells was significantly higher compared to the uninfected controls (4.2 ± 0.8%, p < 0.05)." (PMID 23963354, 2013). "Next, the antigen presenting capacity of HVEM−/− CD8α+ DCs was examined following intravenous infection with rVACV-WR-OVA." (PMID 24205056, 2013). "Although blood stage-specific CD8+ T cells contribute little to protective immunity they are efficiently primed during infection in a process that involves cross-presentation mediated by CD8α+ DCs." (PMID 24741372, 2013). "CD8α+ DCs showed a significant decline in bacterial burden after infection with L. monocytogenes L.p.FlaA despite slight increases in maturation state and numbers." (PMID 24349458, 2013). "Upon infection, CD8α+ DCs migrate into the white pulp and present antigen to CD8+ T cells up to 2 days post-infection." (PMID 24349458, 2013). "Upregulation of BTLA on CD8α+ DC was further confirmed by flow cytometry analysis of cells after vitro and in vivo infection with VACV-WR." (PMID 24205056, 2013). "Presumably the CD8α+ DCs cross-present viral antigens acquired from migratory DCs that originated at the site of infection or acquired from small amounts of free virus that reaches the lymph nodes through lymphatic vessels." (PMID 22691604, 2012). "Our OT-I transfer experiments indicate that the ideal conditions for T-cell priming are found somewhere between days 3–7, whereas the various defects we observed within the old CD8α+ DC subset occurred between 14 h and 3 days post-infection." (PMID 22862959, 2012). "The age-related impaired upregulation of costimulatory molecules became more pronounced on day 1–3 post-infection, with old CD8α+ DC failing to upregulate any of them." (PMID 22862959, 2012). "Further, aged CD8α+ DC showed impaired uptake of the bacteria at very early time points following infection." (PMID 22862959, 2012). "Recent findings have shown Lm specifically in splenic CD8a+ DCs shortly after intravenous infection." (PMID 22912878, 2012). "Although the bacterial burden eventually reached equivalent levels in adult and old animals, the alteration of the early stages of infection correlated with a reduced or bimodal expression of costimulatory molecules on the CD8α+ DC subset in old mice." (PMID 22862959, 2012). "In adult animals, Lm escapes the phagosome rapidly, with ∼50% of the bacteria within the CD8α+ DC subset located in the cytosol within 6 h following i.v. infection." (PMID 22862959, 2012). "There were very few bacteria recovered from other DC subsets at 14 h post-infection, suggesting that the pattern of infection remains the same in aged mice, with CD8α+ DC being the primary reservoir of viable intracellular bacteria." (PMID 22862959, 2012). "In mice, there are migratory DC subsets including epidermal Langerhans cells (LCs), CD11b+ CD103− and CD11b− CD103+ dermal DCs, LN-resident DCs comprising both CD8α+ and CD8α− DCs, and inflammatory DCs recruited during infection." (PMID 22279590, 2012).
infection (continued). "DC development is dependent on the growth factor Flt3L, and exogenous administration has been shown to both increase the number of CD8α+ DC in the spleen of young mice and the bacterial burden in the spleen following infection with Lm." (PMID 22862959, 2012). "Upon infection, low levels of TNFα were detected from CD11b+ DCs and more significant levels of IL-12 p70 were detected from CD8α+ DCs." (PMID 21559416, 2011). "Three days post infection with Ye the number of splenic CD8α+ and CD4+ DCs was reduced by 50% and 90%, respectively." (PMID 21124820, 2010). "CD8α+ DCs have been shown to produce high levels of IL-12 in vivo upon microbial stimulation or infection." (PMID 21124820, 2010). "In particular, we have reported that CD8α+ DC isolated from Chlamydia muridarum infected mice are more potent in inducing protection against challenge infection with the same Chlamydia species than CD8− DC." (PMID 20174628, 2010). "In infection with Toxaplasma gondii, CD8α DC play a clearly established role in MHC class II presentation." (PMID 18301768, 2008). "Analysis of model-derived results show that lung granulomas from asymptomatic mice have a characteristic spatial profile consisting of higher CD4+ and CD8a+ T cell densities, closer B cell proximity to bronchiolar epithelium, and increased T cell-macrophage proximity in asymptomatic M.tb infection." (PMID 41659494, 2026). "Additionally, WCCs had higher levels of CD3+CD4+ T lymphocytes and lower levels of CD3+CD8α+ T lymphocytes, both before and after infection, compared to RWFCs." (PMID 40941329, 2025). "Notably, the proportions of CD8αα+ T cells within the CD8α+ T population and CD8α+ γδ T cells within the γδ T cell population were also elevated in PBMCs during early infection in both infected groups." (PMID 40733525, 2025). "Moreover, double positive T cells (CD4 + CD8α +) increased in the blood of chickens after infection with WT strain when compared with PBS controls (p < 0.05)." (PMID 38822378, 2024). "Similarly, rL. lactis treatment followed by infection with C. perfringens increased the frequency of these cells in duodenum (p ≤ 0.005), jejunum (p ≤ 0.0001) and cecal tonsils (p ≤ 0.01) CD3ζ + CD8α + γδ T cells when compared to control chickens." (PMID 38164397, 2023). "We then studied whether NKp46+CD103- ILC1s and innate CD103+CD8α+/- IELs expand in the epithelium upon infection." (PMID 37744354, 2023). "Direct control of infection by CD8+ T cells has been demonstrated by experiments in simian immunodeficiency virus (SIV)- or simian-human immunodeficiency virus (SHIV)-infected nonhuman primates (NHPs) in which CD8α or CD8β depletion led to an increase in viral load." (PMID 37751362, 2023). "In addition, CTL (CD8a+/CD3+ T cell) numbers were significantly decreased after infection with live Fn and killed Fn (K-Fn) for 48 h." (PMID 37723150, 2023). "Furthermore, the protective immunity against intracellular pathogen infection and direct antibacterial activity of CD8α+ T cells have been demonstrated in carp." (PMID 37073166, 2022). "Infection with the highly virulent ASFV strain Armenia2007 resulted in increased γδ T cell frequencies or differentiation into CD8α+ effector cells in the blood, gastrohepatic lymph nodes, and spleens of infected wild boar, while no such response was detectable in domestic pigs." (PMID 35215216, 2022). "STAB-1 could be required for the proper migration, position, and function of other immune cells, in particular CD8α+ dendritic cells of the splenic marginal zone that were shown to be an obligate cellular entry point for a productive infection by Lm." (PMID 34374322, 2021). "CD8α cDC1 have been shown to be a cellular entry point for infection with Listeria monocytogenes." (PMID 33758366, 2021). "At 22–30 days post-infection, IV exclusion was performed and negatively enriched pooled groups of spleens (3–5 spleens/sample, n = 3) or mLNs (15–25 mLNs/sample, n = 2) were stained for CD8α, CD90.1, CD69, and CD103." (PMID 34143731, 2021).
infection (continued). "The importance of CD8α DCs and NK cells was revealed from experiments conducted in mice lacking CCR5, IRF8, or basic leucine zipper transcription factor ATF-like 3 (BATF3), a transcription factor required for the development of CD8α DCs, as all of them succumb quickly to the infection." (PMID 33178630, 2020). "Moreover, frequencies of CD2+CD8α+ γδ T cells increased in ileum of gnotobiotic pigs following colonization with probiotic Lactobacilli or infection with human rotavirus, while CD2+CD8α− frequencies decreased." (PMID 32612605, 2020). "Because CD8α+ DCs mediate early secretion of IL-12 upon infection, we reasoned that adding exogenous IL-12 might compensate for their absence." (PMID 32669460, 2020). "We found that all mice vaccinated with CD8α ALN-1 survived the challenge infection with pH1N1." (PMID 32714571, 2020). "Further, we could show the presence of and increase in CD8αα expressing αβ as well as CD8α+ γδ T cells in mucosa from respiratory tract after infection in pigs, indicating that these cells have the same dual role as in humans." (PMID 31539406, 2019). "Similarly, infection of CD8α−/− mice with RRV results in increased levels of RRV RNA in the quadriceps at 14 and 21 dpi, but equal levels of virus is detected in the ankle, compared to wild type mice." (PMID 31736977, 2019). "The CD8α+ DCs accumulated and activated at the site of infection, i.e., the liver in response to sporozoites and may take up LS antigen from the apoptotic hepatocytes." (PMID 29472929, 2018). "In addition, in OT-I cells isolated from mice depleted of langerin+ CD8α+ DC during infection, the proportion of IFN-γ+ OT-I cells in response to in vitro stimulation with OVA257–265 peptide was diminished compared to non-depleted mice." (PMID 29867941, 2018). "Thus, we concluded that the presence of CD8α+ DCs is essential for ISG15 to be able to boost IL-1β levels during infection." (PMID 29891555, 2018). "In langerin+ CD8α+ DC-depleted mice, a significant increase in spleen bacterial burden was evident 1 week after infection, compared to non-depleted mice, and this difference was maintained until 3 weeks after infection when spleen bacterial counts peaked." (PMID 29867941, 2018). "The lower expression of cd4-1, cd4-2, cd8α and cd8β in head kidney and the increased expression of the same genes in anterior intestine indicate that both TH cells and CTLs were modulated during the infection." (PMID 30064468, 2018). "Allogeneic T cell stimulation by spleen cells of LDV‐infected wild type, but not TLR‐7‐deficient, mice was severely compromised after infection which coincided with selective elimination of CD11b+ and CD8α+ cDCs from the spleen." (PMID 28474504, 2017). "We detected a small amount of CD8α+ DCs in the spleen of Batf3−/− mice at 9w post-infection." (PMID 28646891, 2017). "Then we detected a small amount of CD8α+ DCs in the spleen of Batf3−/− mice at 9w post-infection." (PMID 28646891, 2017). "This excessive necrosis may also result from the cytotoxic activity of CD8α+ T cells, acting as effector cells which was reported for the caecum of chickens following infections with the virulent protozoan parasite Eimeria tenella." (PMID 28662952, 2017). "Therefore, the present study aimed to assess the role of MIF in the maturation of conventional CD8α+ and CD11b+ DCs during the acute infection with avirulent T. gondii ME49 strain." (PMID 27057101, 2016). "Interestingly, both TMUV-infected and CD8α+ positive cells are widely scattered in the brain during infection." (PMID 27150912, 2016). "This antigen is encoded on sporozoites and PbT1 cells are able to protect mice from liver-stage challenge infection following a spleen-centered CD8α+ dendritic cell-dependent immune response, indicating that the antigen may be partly cross-presented." (PMID 27113469, 2016).